XRCC6 (X-ray repair cross complementing 6)
Description:
DNA-binding protein critical for the DNA damage response, specifically in repairing double-strand breaks (DSBs) via the classical non-homologous end joining (NHEJ) pathway. It forms a heterodimer with XRCC5 (Ku80), creating the Ku70:Ku80 heterodimer (Ku complex), which serves as a DNA end-binding complex. It primarily binds DSBs and recruits essential repair factors, assembling the core long-range NHEJ complex to facilitate the alignment and ligation of broken DNA ends. This pathway ensures the rapid repair of cytotoxic and mutagenic DSBs and contributes to the generation of diversity in T-cell receptors and antibodies through mechanisms such as V(D)J recombination. Likely acts as a 5'-deoxyribose-5-phosphate lyase (5'-dRP lyase), catalyzing the beta-elimination of the 5'-deoxyribose-5-phosphate at abasic sites near DSBs. This activity cleans the termini of abasic sites, a common form of nucleotide damage, preparing broken ends for ligation. It may also possess 3'-5' DNA helicase activity, although this has not been confirmed in vivo, and its physiological significance remains unclear. Beyond DNA repair, the protein contributes to telomere maintenance. It is also implicated in transcriptional regulation, acting as a cofactor for various transcription factors. It plays a role in the regulation of DNA virus-mediated innate immune response by assembling into the HDP-RNP complex, a complex that serves as a platform for IRF3 phosphorylation and subsequent innate immune response activation through the cGAS-STING pathway. Can also bind RNAs and recruits PRKDC to a wide range of cellular RNAs, including the U3 small nucleolar RNA, playing a role in the biogenesis of ribosomal RNAs. Additionally, it negatively regulates apoptosis by interacting with BAX, sequestering it from the mitochondria, and may possess deubiquitination activity targeting BAX.
Synonyms: CTC75; CTCBF; Ku70; TLAA; G22P1; D22S731; D22S671; ML8
Tractability: Small molecule: a structure with a bound ligand is known. Antibody: its Gene Ontology location is reachable by antibodies, with high confidence. PROTAC: UniProt records ubiquitination sites on it; ubiquitination databases record sites on it; its protein half-life has been measured; a small molecule that binds it is known.
Target class: Enzyme; Hydrolase
Gene: Protein-coding gene on chromosome 22 (41,620,786 to 41,664,087, forward strand). Ensembl gene ENSG00000196419.
Subcellular location: Nucleus; Chromosome; Cytoplasm
Subcellular location (Human Protein Atlas): Nucleoplasm
Pathways (Reactome):
Immune System: Cytosolic sensors of pathogen-associated DNA; IRF3-mediated induction of type I IFN; Neutrophil degranulation
DNA Repair: Nonhomologous End-Joining (NHEJ)
Disease: 2-LTR circle formation
Gene Ontology:
Molecular function: 5'-deoxyribose-5-phosphate lyase activity; ATP hydrolysis activity; ATP-dependent activity, acting on DNA; class I DNA-(apurinic or apyrimidinic site) endonuclease activity; cyclin binding; DNA end binding; DNA helicase activity; double-stranded telomeric DNA binding; protein binding; protein-containing complex binding; RNA binding; scaffold protein binding; transcription cis-regulatory region binding; DNA binding; double-stranded DNA binding; telomeric DNA binding; 3'-5' DNA helicase activity; damaged DNA binding
Biological process: activation of innate immune response; cellular response to gamma radiation; double-strand break repair via classical nonhomologous end joining; double-strand break repair via nonhomologous end joining; negative regulation of DNA-templated transcription; positive regulation of DNA-templated transcription; positive regulation of transcription by RNA polymerase II; regulation of smooth muscle cell proliferation; positive regulation of lymphocyte differentiation; recombinational repair; telomere maintenance; cellular hyperosmotic salinity response; cellular response to X-ray; immune system process; positive regulation of immune system process; response to ionizing radiation
Cellular component: chromosome; chromosome, telomeric region; cytoplasm; DNA-dependent protein kinase complex; DNA-dependent protein kinase-DNA ligase 4 complex; Ku70:Ku80 complex; membrane; nonhomologous end joining complex; nucleolus; nucleoplasm; nucleus; protein-containing complex; protein-DNA complex; transcription regulator complex; cytosol; extracellular region; ficolin-1-rich granule lumen; nuclear telomere cap complex; secretory granule lumen
Genetic constraint (gnomAD): Loss-of-function variants: 5 observed, 61.16 expected, observed/expected ratio (o/e) 0.0818, 90% interval 0.042 to 0.17. The upper end of that interval is the gene's LOEUF score, 0.17, which puts it in group 1 of 6, group 1 being the genes least tolerant of losing a copy. Missense variants: 436 observed, 749.87 expected, observed/expected ratio (o/e) 0.58, 90% interval 0.54 to 0.63. Synonymous variants: 267 observed, 276.05 expected, observed/expected ratio (o/e) 0.97, 90% interval 0.87 to 1.07.
Homologues: Orthologues: chimpanzee XRCC6 (100% identical), macaque XRCC6 (99% identical), rabbit XRCC6 (87% identical), pig XRCC6 (85% identical), guinea pig XRCC6 (84% identical), mouse Xrcc6 (83% identical), rat Xrcc6 (83% identical), dog XRCC6 (82% identical), tropical clawed frog xrcc6 (66% identical), zebrafish xrcc6 (58% identical), Caenorhabditis elegans cku-70 (25% identical), Drosophila melanogaster Irbp (24% identical), and 1 more. Paralogues in human: XRCC5 (17% identical).
Diseases named in the same sentence as XRCC6 in open-access papers:
XRCC6 is named in the same sentence as 154 diseases in open-access papers, as found by Europe PMC text mining. Sharing a sentence is not in itself a finding about the gene and the disease. The quoted sentences say what the papers report.
breast cancer (42 papers, 2009 to 2025). A primary or metastatic malignant neoplasm involving the breast. "Studies show that the XRCC6 polymorphism is correlated with the occurrence and development of breast cancer." (PMID 34484285, 2021). "This study provides new evidence that XRCC5 rs16855458 is associated with breast cancer risk among Chinese women, and that XRCC6 rs2267437 is associated with the risk of ER−/PR− breast cancer." (PMID 33734613, 2021). "The CG + GG genotype of XRCC6 rs2267437 was associated with an increased risk of ER−/PR− breast cancer (CG + GG vs. CC: OR = 1.54, 95% CI = 1.12–2.13, p = 0.008) after Bonferroni correction." (PMID 33734613, 2021). "The effects of potential interactions between target (XRCC5 and XRCC6) SNPs and smoking, alcohol consumption, and sleep satisfaction on breast cancer risk were analyzed." (PMID 33734613, 2021). "There are reports which show that XRCC6-61C/G polymorphism is associated with an increased risk of cancers, including breast cancer and gliomas." (PMID 33685509, 2021). "This study aimed to determine the influence of XRCC5 and XRCC6 polymorphisms on breast cancer risk, and potential interactions with cigarette smoking, alcohol consumption, and sleep satisfaction." (PMID 33734613, 2021). "XRCC5 rs16855458 was associated with breast cancer risk, and XRCC6 rs2267437 was associated with the risk of ER−/PR− breast cancer." (PMID 33734613, 2021). "Antagonistic interaction between XRCC5 rs16855458 and alcohol consumption, and synergistic interaction between XRCC6 rs2267437 and sleep satisfaction were also found to affect breast cancer risk." (PMID 33734613, 2021). "XRCC6 interacts with Msx2 (a known TBX3 interactor) and Runx2 (a TBX3 target) and mutations in XRCC6 are associated with breast cancer risk and estrogen exposure." (PMID 24675841, 2014). "Moreover, potential interactions between XRCC5 rs16855458 and alcohol consumption, and between XRCC6 rs2267437 and sleep satisfaction were identified in relation to breast cancer risk." (PMID 33734613, 2021). "However, the specific mechanism between XRCC6 rs2267437 variation and ER+/PR+ breast cancer risk is still unclear and further investigation is required." (PMID 33734613, 2021). "Since XRCC6 rs2267437 was associated with dysfunctional DNA damage repair, a potential synergistic effect between rs2267437 and poor sleep patterns can further increase the risk of breast cancer." (PMID 33734613, 2021). "Moreover, an antagonistic interaction between XRCC5 rs16855458 and alcohol consumption (pinteraction = 0.017), and a synergistic interaction between XRCC6 rs2267437 and sleep satisfaction were associated with breast cancer risk (pinteraction = 0.0497)." (PMID 33734613, 2021). "The data revealed that XRCC5 rs16855458 was associated with increased breast cancer risk in the co‐dominant genetic model, and the CG + GG genotype of XRCC6 rs2267437 was associated with an increased risk of ER−/PR− breast cancer, even after Bonferroni correction." (PMID 33734613, 2021). "Moreover, polymorphisms in XRCC6 gene have been shown to increase breast cancer susceptibility as well as other types of cancer." (PMID 29108258, 2017). "The XRCC6 -61C>G polymorphism, rs2267437, was located in the promoter region and it is established that this SNP could influence the expression level and stability of the Ku70 protein in breast cancer cells and renal cell carcinoma tissues." (PMID 28421111, 2017). "In breast cancer, there are NHEJ genes XRCC5/Ku80 and XRCC6/Ku70 polymorphisms associated with breast cancer risk and chromosomal radiosensitivity." (PMID 39334297, 2024). "We confirmed the interaction of HMGA2 with XRCC6/ Ku70 by co-IP in human MDA231 breast cancer cells." (PMID 36835656, 2023). "Some evidence demonstrated the correlation between dysfunction of XRCC6 and tumorigenesis of various cancer types, such as breast cancer and colorectal cancer." (PMID 36224658, 2022).
breast cancer (continued). "The predicted direction of association with contralateral breast cancer risk was uniformly increased for the LIG4, NHEJ1, and XRCC5 genes while uniformly decreased for the XRCC4 and XRCC6 genes." (PMID 31560388, 2019). "On the other hand, the high expression of XRCC6 in BRCAX individuals affected with breast cancer remains to be elucidated." (PMID 29108258, 2017). "The CG + GG genotype of XRCC6 rs2267437 was associated with an increased risk of estrogen receptor‐negative/progesterone receptor‐negative (ER−/PR−) breast cancer (CG + GG vs. CC: OR = 1.54, 95% CI = 1.12–2.13, p = 0.008) after Bonferroni correction." (PMID 33734613, 2021). "XRCC5 rs16855458 and rs9288516 have potential biological functions as they cause changes in the binding sites of transcription factors, and correlate with risk for hepatocellular carcinoma, whereas XRCC6 rs2267437 and XRCC5 rs3835 were correlated with breast cancer risk in European women." (PMID 33734613, 2021). "Breast cancer risk associated with XRCC5 and XRCC6 polymorphisms might vary according to alcohol consumption and sleep satisfaction, respectively, and merit further investigation." (PMID 33734613, 2021). "(D) Box-plots of HR (BRCA1, BRCA2, ATR) and NHEJ (PRKDC, XRCC5, XRCC6) protein expression levels (ratio to pool) in the different groups of breast cancer cell lines according to AZD1775 response characteristics (recovering-basal, sensitive-basal and recovering-luminal)." (PMID 32628111, 2020). "Malfunction of the XRCC6 gene is observed in ovarian cancer and breast cancer." (PMID 22415234, 2012). "Furthermore, the CG + GG genotype of XRCC6 rs2267437 was found to be associated with an increased risk of ER−/PR− breast cancer even after Bonferroni correction, but not with ER+/PR+ breast cancer." (PMID 33734613, 2021). "We focused on XRCC6/Ku70 and demonstrated co-precipitation of Ku70 with HMGA2 from MDA231 human breast cancer cell nuclear extracts." (PMID 36835656, 2023). "On the other hand, activation of CASP3 is involved in the initiation of cell apoptosis, inhibition of NMT1 regulates breast cancer oncogenesis by the JNK pathway, and inactive XRCC6 fails to protect genomic integrity." (PMID 32419250, 2020).
colorectal cancer (21 papers, 2006 to 2026). A primary or metastatic malignant neoplasm that affects the colon or rectum. "In this study, we investigated the cellular dynamics of a human colorectal cancer cell line (HCT116) that is engineered for conditional deletion of XRCC6 gene (codes for Ku70 protein) by using live-cell imaging and confocal microscopy technologies." (PMID 33855027, 2021). "A previous study had also reported higher mRNA and protein levels of PRKDC in colorectal cancer tissues compared to normal tissues, which also exhibited a positive correlation with expression of XRCC6 and XRCC5." (PMID 33195430, 2020). "We found that, upon conditional deletion of XRCC6 that codes for Ku70, HCT116 human colorectal cancer cells gain a parasitic lifestyle that is characterized by the continuous cycle of host cell exploitation." (PMID 33855027, 2021). "Most promising and meaningful modifications were observed on the surface of vitamin D-binding protein (VDBP), complement C4-A (CO4A), X-ray repair cross-complementing protein 6 (XRCC6), Plasma protease C1 inhibitor (IC1), and albumin (ALBU), which are related to colorectal cancer developing." (PMID 32660089, 2020).
hepatocellular carcinoma (21 papers, 2011 to 2025). A malignant tumor that arises from hepatocytes. "Overexpression of XRCC5 and XRCC6 was significantly associated with the clinical stage and pathological grade of hepatocellular carcinoma." (PMID 37679817, 2023). "The association between the expression of XRCC6 and the risk of cancer, such as lung cancer, glioma, hepatocellular carcinoma and so on, has been studied by several experiments." (PMID 27455247, 2016). "Although the association of the XRCC6 gene with cancer has been studied in some cancers, such as hepatocellular carcinoma, breast, oral, and colorectal cancers, no research has been conducted to assess the relationship between thyroid cancer and XRCC6 gene polymorphisms." (PMID 39734356, 2024). "Similar to our findings, it has been reported that different XRCC6 genotypes may contribute to susceptibility to another disease related to virus infection, namely, hepatocellular carcinoma (HCC)." (PMID 36312587, 2022). "Extensive research on hepatocellular carcinoma (HCC) cell lines has demonstrated that elevated DNA-PK levels are closely associated with increased expression of key DNA repair proteins, particularly XRCC6 and XRCC5." (PMID 40256842, 2025). "PARP6 was confirmed can inhibit the expression of XRCC6 by inducing degradation and thus regulate the Wnt/β-catenin pathway, which contributes to the suppression of hepatocellular carcinoma." (PMID 36845744, 2023). "ARTD17/PARP6, considered as a tumor suppressor, limits the proliferation and spreading ability of the hepatocellular carcinoma cells by degrading XRCC6/Ku70 and by regulating the Wnt/ß-catenin pathway." (PMID 33440786, 2021). "PRKDC, PARP1, NPM1 and XRCC6 are hepatocellular carcinoma over-expression genes which modulate cell cycle regulation network through the modulation of UBC." (PMID 24564241, 2013). "In addition, PARP6 reportedly inhibits XRCC6 expression by inducing degradation and thus affects the Wnt/β-catenin signaling pathway, leading to the suppression of hepatocellular carcinoma." (PMID 35836822, 2022). "Moreover, they observed a significant correlation between the expression of XRCC5 and XRCC6 and the infiltration of B cells, CD4+ T cells, CD8+ T cells, macrophages, neutrophils, and dendritic cells in hepatocellular carcinoma." (PMID 37679817, 2023).
lung carcinoma (20 papers, 2012 to 2025). "XRCC6 was found to be upregulated in lung adenocarcinoma and associated with the cell cycle, with knockdown of XRCC6 inhibiting lung cancer cell proliferation." (PMID 39769336, 2024). "CCK-8 and EdU cell proliferation assays indicated that the knockdown of XRCC6 markedly reduced the proliferation of lung cancer cells A549 and H1299." (PMID 39769336, 2024). "Further in vitro experiments showed that knocking down XRCC6 reduced the proliferative capacity of lung cancer cells, while overexpression of XRCC6 rescued H2O2-induced DNA damage and cellular senescence, implying a significant biological role of XRCC6 in lung adenocarcinoma." (PMID 39769336, 2024). "Clinically, XRCC5 and XRCC6 single nucleotide polymorphisms as well as epigenetic silencing of these genes can lead to the development of multiple cancers, such as CRC, breast and lung cancer." (PMID 26755646, 2016). "As instrumental variables, amino acid variations in the model genes XRCC6 and PRKDC considerably affected apoptotic protein levels, macrophage markers, and macrophage secretion factors, thereby altering lung cancer outcomes." (PMID 39660143, 2024).
neuroblastoma (17 papers, 2012 to 2024). Neuroblastoma (NB) is the most common solid, extracranial childhood tumor. "Ku70 (Lupus Ku autoantigen protein p70; XRCC6) is a DNA-binding component of the non-homologous end joining (NHEJ) double strand break (DSB) repair complex, and Ku70 acetylation has previously been shown to mediate neuroblastoma cell apoptosis." (PMID 37957138, 2023).
prostate carcinoma (16 papers, 2011 to 2022). A carcinoma that arises from epithelial cells of the prostate gland. "In addition, XRCC6 is involved in the poor prognosis of human osteosarcoma cells and prostate cancer." (PMID 34671397, 2021).
colon cancer (14 papers, 2009 to 2025). "Our recent studies demonstrated a DNA damage-independent interaction between DDB1/DDB2 and XRCC5/XRCC6 in colon cancer cells." (PMID 30410671, 2018). "To determine the expression pattern of core NHEJ genes in colon cancer, we performed Oncomine analysis for XRCC6 (Ku70), XRCC5 (Ku80), PRKDC (DNA-PKcs), XRCC4 (XRCC4), LIG4 (DNA ligase 4), NHEJ1 (XLF), and PAXX (PAXX/XLS)." (PMID 33195430, 2020). "Our analysis revealed elevated mRNA and protein expression of XRCC6 (Ku70) and XRCC5 (Ku80) in colon cancer compared to normal colon tissue." (PMID 33195430, 2020).
melanoma (11 papers, 2010 to 2025). A malignant, usually aggressive tumor composed of atypical, neoplastic melanocytes. "In a melanoma cell line model, it has been shown that mutant BRAF inhibition may increase DNA damage by downregulation of NHEJ pathway genes, including XRCC6, XRCC5, and PRKDC." (PMID 33195430, 2020).
lupus (7 papers, 2012 to 2023). "Of note, the XRCC6 protein, which is involved in NHEJ required for DSB repair pathway and V(D)J recombination, is a well-established lupus autoantigen." (PMID 31861764, 2019).